TRIM10 (tripartite motif containing 10)
Description:
E3 ligase that plays an essential role in the differentiation and survival of terminal erythroid cells. May directly bind to PTEN and promote its ubiquitination, resulting in its proteasomal degradation and activation of hypertrophic signaling (By similarity). In addition, plays a role in immune response regulation by repressing the phosphorylation of STAT1 and STAT2 in the interferon/JAK/STAT signaling pathway independent of its E3 ligase activity. Mechanistically, interacts with the intracellular domain of IFNAR1 and thereby inhibits the association between TYK2 and IFNAR1.
Synonyms: RFB30; RNF9; HERF1
Tractability: No criterion of Open Targets' tractability assessment is met for any kind of drug.
Gene: Protein-coding gene on chromosome 6 (30,151,943 to 30,161,211, reverse strand). Ensembl gene ENSG00000204613.
Subcellular location: Cytoplasm
Pathways (Reactome):
Immune System: Interferon gamma signaling
Gene Ontology:
Molecular function: protein binding; ubiquitin protein ligase activity; metal ion binding; zinc ion binding
Biological process: positive regulation of cGAS/STING signaling pathway; protein K27-linked ubiquitination; protein K29-linked ubiquitination; innate immune response; antiviral innate immune response; host-mediated suppression of symbiont invasion
Cellular component: cytoplasm
Genetic constraint (gnomAD): Loss-of-function variants: 39 observed, 39.61 expected, observed/expected ratio (o/e) 0.98, 90% interval 0.76 to 1.29. The upper end of that interval is the gene's LOEUF score, 1.29, which puts it in group 5 of 6, group 1 being the genes least tolerant of losing a copy. Missense variants: 593 observed, 622.02 expected, observed/expected ratio (o/e) 0.95, 90% interval 0.89 to 1.02. Synonymous variants: 257 observed, 250.07 expected, observed/expected ratio (o/e) 1.03, 90% interval 0.93 to 1.14.
Homologues: Orthologues: macaque TRIM10 (98% identical), rabbit TRIM10 (88% identical), pig TRIM10 (86% identical), mouse Trim10 (84% identical), rat Trim10 (83% identical), dog TRIM10 (82% identical), chimpanzee TRIM10 (76% identical), guinea pig TRIM10 (65% identical). Paralogues in human: TRIM15 (43% identical), TRIM26 (41% identical), TRIM27 (35% identical), TRIM39 (35% identical), TRIM41 (32% identical), TRIM58 (32% identical), TRIM11 (31% identical), TRIM21 (31% identical), TRIM7 (30% identical), TRIM4 (29% identical), TRIM17 (26% identical), TRIM60 (26% identical), and 68 more.
Diseases named in the same sentence as TRIM10 in open-access papers:
TRIM10 is named in the same sentence as 25 diseases in open-access papers, as found by Europe PMC text mining. Sharing a sentence is not in itself a finding about the gene and the disease. The quoted sentences say what the papers report.
Parkinson disease (3 papers, 2020 to 2024). A progressive degenerative disorder of the central nervous system characterized by loss of dopamine producing neurons in the substantia nigra and the presence of Lewy bodies in the substantia nigra and locus coeruleus. "However, recent research has shown that TRIM10 is involved in Parkinson's disease (PD) and other autoimmune diseases." (PMID 34435051, 2021).
schizophrenia (3 papers, 2017 to 2024). A major psychotic disorder characterized by abnormalities in the perception or expression of reality. "In the same covariate analyses, when considering trend-significant associations, we identified genes such as TRIM10 and GAS7, associated with schizophrenia, MACROH2A1, related to autism-like behaviors, and ADORA2A, associated with anxiety disorders." (PMID 39020437, 2024). "Several genes that initially appeared significant without correction—such as PEAK1 for diabetes, TRIM10 for schizophrenia, and CCDC57 for chronic kidney disease—fell below the Bonferroni significance threshold after correction, underscoring the importance of this adjustment." (PMID 37904952, 2024).
anemia (2 papers, 2022 to 2025). A reduction in the number of red blood cells, the amount of hemoglobin, and/or the volume of packed red blood cells. "Regulating the expression or selectively inhibiting the pathological activities of TRIM10 paralogs could help prevent the onset and progression of anemia." (PMID 41168352, 2025).
cardiac hypertrophy (2 papers, 2020 to 2021). "Tripartite motif containing 10 (TRIM10) is also associated with immune response, and regulates cardiac hypertrophy through the PTEN/AKT pathway." (PMID 34753383, 2021). "According to these results, we speculate that TRIM10‐mediated pathological cardiac hypertrophy may be associated with AKT‐ or STAT3‐dependent signalling." (PMID 32343488, 2020). "Taken together, our results identify TRIM10 as a potential novel regulator involved in pathological cardiac hypertrophy, mainly through its action on PI3K/AKT signalling." (PMID 32343488, 2020). "To elucidate possible molecular mechanisms of TRIM10, we examined multiple classical signalling pathways potentially involved in cardiac hypertrophy under pressure load." (PMID 32343488, 2020). "Knockout of TRIM10 in mice prevented cardiac hypertrophy induced by hypertrophic stimulation, and this effect was further verified in NRCMs." (PMID 32343488, 2020). "In this study, neonatal rat cardiomyocytes (NRCMs) and TRIM10‐knockout mice were subjected to phenylephrine (PE) stimulation or transverse aortic constriction (TAC) to induce cardiac hypertrophy in vitro and in vivo, respectively." (PMID 32343488, 2020). "The results of this study reveal the involvement of TRIM10 in pathological cardiac hypertrophy, which may occur by prompting of PTEN ubiquitination and subsequent activation of AKT signalling." (PMID 32343488, 2020). "In this study, we aimed to examine whether TRIM10 is involved in cardiac hypertrophy and, if so, its molecular target." (PMID 32343488, 2020). "Collectively, these results indicate that TRIM10 may lead to ubiquitination and degradation of PTEN, which could be an underlying reason for AKT signalling inhibition in cardiac hypertrophy processes." (PMID 32343488, 2020). "Altogether, these results suggest that TRIM10 expression is increased in cardiomyocytes responding to hypertrophic stimuli and may be involved in the pathological process of cardiac hypertrophy." (PMID 32343488, 2020). "In the present study, we identified a novel role of TRIM10 in cardiac hypertrophy." (PMID 32343488, 2020). "We next investigated whether TRIM10 could modulate the development of cardiac hypertrophy by transfecting NRCMs with siRNA‐TRIM10, Ad‐Trim10, scramble‐siRNA (as siRNA‐con) or Ad‐GFP." (PMID 32343488, 2020). "At a biochemical level, it is generally accepted that similar structures perform similar functions; thus, TRIM10 may be involved in cardiac hypertrophy." (PMID 32343488, 2020). "However, functional roles and molecular mechanisms of TRIM10 during cardiac hypertrophy remain to be elucidated." (PMID 32343488, 2020). "However, little is known about functional roles of TRIM10 in regulating cardiac hypertrophy." (PMID 32343488, 2020). "Therefore, TRIM10 may be a promising target for treatment of cardiac hypertrophy." (PMID 32343488, 2020).
acute myeloid leukemia (1 paper, 2026). Acute myeloid leukemia (AML) is a group of neoplasms arising from precursor cells committed to the myeloid cell-line differentiation. "The journal retracts the article "TRIM10 is downregulated in acute myeloid leukemia and plays a tumor suppressive role via regulating NF-κB pathway" [...]." (PMID 42102023, 2026).
autoimmune disease (1 paper, 2021). A disorder resulting from loss of function or tissue destruction of an organ or multiple organs, arising from humoral or cellular immune responses of the individual to their own tissue constituents. "Silencing of TRIM10 reduced apoptosis and reactive oxygen species levels in a cellular model of PD, which suggests a potential role of TRIM10 in PD and other autoimmune diseases." (PMID 34435051, 2021).
cervical cancer (1 paper, 2022). A primary or metastatic malignant neoplasm involving the cervix. "Totally, 13 genes including HLA-A and -J, TRIM10, 15, 26, 31, 40 and others experienced SCNA loss in advanced stage cervical cancer." (PMID 35205332, 2022).
cognitive decline (1 paper, 2024). "TRIM10 is a gene that has been shown previously to be hypermethylated in both the brain and blood of patients with PD compared to controls, which is interesting as serum NfL is associated with cognitive decline in patients with PD." (PMID 39193893, 2024).
colorectal cancer (1 paper, 2025). A primary or metastatic malignant neoplasm that affects the colon or rectum. "In colorectal cancer, six genes were positively correlated: ANLN, ACOT7, OSBPL3, SEC61G, DDX56, and TRIM10." (PMID 40765570, 2025).
hemoglobin disorders (1 paper, 2024). "Here, we have used a general strategy to assess the capability of two erythroid cell–enriched E3 ubiquitin ligases, TRIM10 and TRIM58, to degrade a POI, BCL11A, which is a validated target for reactivation of HbF in hemoglobin disorders." (PMID 39675716, 2024).
Sepsis (1 paper, 2023). Sepsis is defined as life-threatening organ dysfunction caused by a dysregulated host response to infection. "TRIM10 in M23 is of the same gene family member, but with unexplored roles in sepsis." (PMID 38071387, 2023).
cancer (3 papers, 2018 to 2024). A tumor composed of atypical neoplastic, often pleomorphic cells that invade other tissues. "In particular, six candidates (TRIM10, TRIM15, TRIM26, TRIM39-RPP21, TRIM62, and TRIM66) are members of the large tripartite motif (TRIM) family that consists of ubiquitin ligases involved in both innate immunity and cancer progression." (PMID 30102725, 2018).
infection (1 paper, 2020). The state of being infected such as from the introduction of a foreign agent such as serum, vaccine, antigenic substance or organism. "Conversely, Ad‐TRIM10 infection markedly aggravated the effects induced by PE stimulation." (PMID 32343488, 2020).
TRIM10 also shares sentences with these, for which no sentence is quoted: Tumor (3 papers); agranulocytosis (1); anxiety disorder (1); autism (1); chronic kidney disease (1); diabetes (1); leukemia (1); liver cancer (1); Moyamoya disease (1); myeloid leukemia (1); prostate carcinoma (1); psychiatric disorder (1).